IL6 (interleukin 6)
Diseases named in the same sentence as IL6 in open-access papers (continued):
Sharing a sentence is not in itself a finding about the gene and the disease.
inflammatory bowel disease (continued). "Interleukin 6 (IL6) is an inflammatory cytokine; signaling via its receptor (IL6R) is believed to contribute to development of inflammatory bowel diseases (IBD)." (PMID 29775600, 2018). "In a mouse model of inflammatory bowel disease, peritoneal M2 macrophages induced by T. spiralis suppressed the production of pro-inflammatory cytokines such as TNF-α and IL-6, and consequently reduced the severity of inflammation." (PMID 28542159, 2017). "At the same time, Wip1 knockout mice exhibit pro-inflammatory phenotype in skin and intestine in the model of inflammatory bowel disease (IBD) with elevated levels of inflammation-promoting cytokines TNF-α, IL-6, IL-12, IL-17." (PMID 28417018, 2017). "Inflammatory bowel disease was induced by the over-expression of pro-inflammatory cytokines (TNF-α, IL-1, IL-6, and IL-12) and/or the down-regulation of anti-inflammatory cytokines in the polarization of Th1/Th2 cells in colonic mucosa." (PMID 27932984, 2016). "IL-6 as a therapeutic target is currently under investigation in various chronic immune-mediated diseases, including rheumatic arthritis and inflammatory bowel disease (IBD)." (PMID 27869785, 2016). "Moreover, our team has obtained significant results in IBD (inflammatory bowel disease) treatment, by the identification of several compounds inhibiting inflammation mediators like IL-6, NF-ĸβ and COX-2." (PMID 25910265, 2015). "IL-6 plays an inflammatory and regenerative role in inflammatory bowel disease (IBD)." (PMID 24993179, 2014). "The production of proinflammatory cytokines, such as interleukin-6, interleukin-12, and tumor necrosis factor (TNF-α), is universally increased in patients with inflammatory bowel disease." (PMID 23056142, 2012). "In the context of inflammatory bowel disease (IBD), ASX supplementation has been shown to reduce colonic inflammation by downregulating cytokines such as TNF-α, IL-1β, and IL-6, while enhancing endogenous antioxidant defenses including superoxide dismutase and glutathione peroxidase." (PMID 40559644, 2025). "Furthermore, exosomes from human umbilical cord mesenchymal stem cells reduced the severity of inflammatory bowel disease in mice by increasing IL-10 levels and decreasing TNF-α, IL-1β, and IL-6 in the colon tissues." (PMID 40822681, 2025). "HDACi treatment might improve the outcome of autoimmune and autoinflammatory-like inflammatory bowel disease (IBD) or RA through the induction of FLS growth arrest, anti-angiogenic properties, or suppression of pro-inflammatory cytokines like IL-6 and TNF-α." (PMID 39846569, 2025). "In the inflammatory bowel disease (IBD) induced by LPS in human colon mucosal epithelial cells (NCM460), Mor reduced apoptosis, inflammation, and oxidative stress by regulating Bax/Bcl-2, inhibiting TNF-α, IL-1β, IL-6, SOD, MDA, T-AOC, and MPO levels." (PMID 39301568, 2024). "A study indicated that the expression of ATF4 was decreased in inflamed intestinal mucosa of patients with active inflammatory bowel diseases, and overexpression of ATF4 down-regulated inflammatory factors including IL-1β and IL-6, while deprivation of ATF4 promotes intestinal inflammation." (PMID 38913045, 2024). "Likewise, the pre-treatment of NaB obviously represses the expression levels of IL-6 and TNF-α in RAW246.7 macrophages induced by lipopolysaccharide in vitro, suggesting its anti-inflammatory property in inflammatory bowel disease." (PMID 38616256, 2024). "Seven genes IL10, IL4, IL6, IFNG, IL1B, TNF and IL17A, were engaged in Inflammatory bowel disease." (PMID 36989283, 2023). "In addition, EPS which were isolated from L. plantarum YW11 reduced the production of the proinflammatory cytokines (TNFα, IL-1β, IL-6, IFN-γ, IL-12 and IL-18) and up-regulated IL-10, and this resulted in an amelioration of inflammatory bowel disease symptoms." (PMID 36769176, 2023).
inflammatory bowel disease (continued). "Collectively, their findings suggest that the new proliferative factor REG1A, which is regulated by IL-6/IL-22-JAK-STAT3 signaling, may represent an attractive therapeutic target for patients with inflammatory bowel disease." (PMID 35432477, 2022). "Furthermore, Veroniella is a proinflammatory taxon that increases in patients with inflammatory bowel disease and irritable bowel syndrome and promotes the expression of several inflammatory cytokines (TNF-α, IL-6, and IL-1β) in the colon." (PMID 36519162, 2022). "OSM is a member of the interleukin-6 (IL-6) cytokine family and has been previously shown to drive intestinal inflammation in adults with inflammatory bowel disease, and a single nucleotide polymorphism in the OSM locus was associated with increased risk of IBD." (PMID 35410447, 2022). "Previous research on patients with inflammatory bowel disease (IBD) has identified several genes (IL13RA2, TNFRSF11B, STC1, IL-6, and IL-11) that constitute potential biomarkers that can identify patients with limited response to IFX, which is consistent with our study." (PMID 34650991, 2021). "In patients with inflammatory bowel disease, a large population of inflammatory cells infiltrated in the mucosa, excessive inflammatory cytokines including tumor necrosis factor (TNF)-α, interleukin (IL)-18, IL-6, IL-1β were secreted." (PMID 33240089, 2020). "Cytokines such as IL-6, IL-8, MCP-1 and IL-1β are potent pro-inflammatory cytokines, and their elevated levels play crucial roles in the development of several diseases including diarrhea and inflammatory bowel diseases." (PMID 32150574, 2020). "The mechanism of Portulaca extract in alleviation of inflammatory bowel disease could be related to its regulation of inflammatory cytokines (TNF-α, IL-6, and IL-1β), transcription factors (NF-kB and PPAR-γ), and apoptosis." (PMID 29483924, 2018). "An abundance of different cytokines, including IL-6 and TNF-α, can lead to inflammation, which can in turn lead to several diseases, including Alzheimer’s disease, cardiovascular diseases, inflammatory bowel disease, sickness behavior, tumor progression, and so on." (PMID 28545436, 2017). "Last but not least, refractory Inflammatory DiseasesRheumatoid arthritis (RA) and inflammatory bowel disease (IBD) involve localized overexpression of pro-inflammatory factors (TNF-α, IL-6) and oxidative stress." (PMID 41560795, 2026). "B. acidifaciens may contribute to lower levels of IL-6 and TNF-α, promotion of IgA production, improvement of intestinal immune function, protection against intestinal pathogens, and reduction of the incidence of inflammatory bowel disease." (PMID 38783703, 2024). "These consecutive occurrences lead to the activation of the pro-inflammatory cytokines, IL-1β, IL-6, and TNF-α, ultimately resulting in the deterioration of the intestinal epithelial cell barrier and significantly contributing to the pathogenesis of inflammatory bowel disease." (PMID 38772090, 2024). "Furthermore, treatment of inflammatory bowel disease (IBD)-induced mice with compound 1 decreased myeloperoxidase activity in colonic extracts and modulated the colon length and serum levels of cytokines such as TNF–α, IFN–γ, IL–6, IL–1β, and IL–10." (PMID 37893090, 2023). "Patients with inflammatory bowel disease (IBD) share a similar inflammatory cytokine profile with acute exacerbation and “cytokine storm”, and such patients could benefit from treatment with interleukin-1 or interleukin-6 antagonists." (PMID 36006279, 2022). "For example, EXO of intestinal lumen aspirates of inflammatory bowel disease IBD patients carries pro-inflammatory factors including TNF-α, IL6, and IL8 in levels higher than that of healthy controls." (PMID 34208697, 2021).
inflammatory bowel disease (continued). "Recently, we could show that elevated fecal calprotectin, a reliable biomarker for activity and inflammation in inflammatory bowel disease (IBD), correlates with serum interleukin-6 (a cytokine that indicates disease severity) in hospitalized COVID-19 patients." (PMID 33438988, 2021). "For example, one recent study found that CSO treatment protected against inflammatory bowel disease (IBD) by reducing the expression of inflammatory cytokines such as TNF-α, IL-1β, IL-6, and IL-17." (PMID 32917229, 2020). "Inflammatory disorders, such as RA, Crohn's disease and inflammatory bowel disease (IBD), have shown increased expression of TNF, IL-1β and IL-6, which contribute to joint erosion and tissue destruction." (PMID 32873150, 2020). "Enhanced expressions of proinflammatory cytokines in mucosal tissues such as interleukin- (IL-) 1β, IL-6, IL-8, tumor necrosis factor- (TNF-) α, and interferon- (IFN-) γ are found in patients with inflammatory bowel disease (IBD)." (PMID 31780866, 2019). "Indeed, in an experimental model of inflammatory bowel disease, CBG reduced IL-1β and IFN-γ levels in inflamed colons, while in a model of Huntington’s disease, CBG was able to decrease the expression of TNF-α and interleukin 6 (IL-6)." (PMID 29986533, 2018). "Patients with inflammatory bowel disease (IBD) had higher VAS (P = 0.03), CRP (P = 0.0009), and IL-6 (P = 0.0003) levels." (PMID 28053373, 2016). "Inflammatory bowel disease (IBD), comprised of Crohn’s disease and Ulcerative colitis, is a chronic inflammatory bowel disease with sustained up-regulation of inflammatory mediators such as TNF-α, IL-6, and IL-1, which themselves are regulated by the activation of NF-κB." (PMID 26205050, 2015). "In this context, the monoclonal antibody, Olamkicept (soluble gp130Fc or sgp130Fc), that specifically inhibits IL-6 trans-signaling without interfering with classic IL-6 signaling, is effective treatment for inflammatory bowel disease (IBD)." (PMID 40114923, 2025). "Our findings suggest that resveratrol may exhibit anti-inflammatory effects in Inflammatory Bowel Disease (IBD) by increasing IL-10 levels and decreasing TNF-α, IL-6, IL-1β, and IL-8 levels." (PMID 38948464, 2024). "In general, inflammatory bowel disease (IBD) patients exhibit an excessive immune response to commensal bacterial antigens, resulting in the release of pro-inflammatory cytokines, such as IL-1β, TNF-α, IL-6, and IL-12." (PMID 37376017, 2023). "Elevated levels of IL-6 have been found to play a pathological role in rheumatoid and juvenile idiopathic arthritis (RA and JIA, respectively), systemic lupus erythematosus (SLE), multiple sclerosis (MS), inflammatory bowel disease (IBD), and allergic asthma." (PMID 27242798, 2016). "Besides, the increased production of IL-1, IL-6, IL-8, TNF-α and TGF-β in the jejunum were detected, indicating that AHBZ2303 or AHBZ2304 infection could induce host inflammatory response and contribute to inflammatory bowel disease, accompanied by significant pathological damage." (PMID 40290474, 2025). "High concentrations or certain structural forms may increase cytokine production (e.g., IL-6, TNF-α) in immune cells, potentially exacerbating inflammation in conditions like inflammatory bowel disease (IBD) depending on concentration and the inflammatory environment." (PMID 39598865, 2024). "However, F. prausnitzii has been shown to produce butyrate resulting in an anti-inflammatory role by inhibiting interleukin (IL-6), the activator of transcription 3 (STAT3)/IL-17 pathway in colorectal colitis having an important role in inflammatory bowel disease (IBD) treatment." (PMID 36671749, 2022). "Inflammatory bowel disease (IBD) is characterized by an imbalanced immune response, leading to a pro-inflammatory phenotype with elevated tissue concentrations of various cytokines including tumor necrosis factor (TNF), interleukin-6 (IL-6), and interferon-γ (IFNγ)." (PMID 31572379, 2019).
osteoarthritis (390 papers, 2005 to 2026). A noninflammatory degenerative joint disease occurring chiefly in older persons, characterized by degeneration of the articular cartilage, hypertrophy of bone at the margins and changes in the synovial membrane. "This suggests they capture inflammatory dynamics more specific to the osteoporotic fracture risk state, as an indirect measure of IL-6 levels, with less interference from osteoarthritis." (PMID 41009701, 2025). "Chronic conditions such as osteoarthritis and cervical spondylosis elevate systemic IL-6 and TNF-α levels, both of which are implicated in neuropathic pain pathogenesis." (PMID 41393290, 2025). "Examples of diagnostic biomarkers include interleukin-6, elevated in synovial fluid of internal derangement and degenerative joint disease, and C-reactive protein, which shows significantly higher salivary levels in internal derangement." (PMID 41164068, 2025). "Although its role in osteoarthritis remains debated, elevated IL-6 levels have been consistently associated with cartilage degradation, disease severity, and pain." (PMID 40668398, 2025). "It is known that osteoarthritis is associated with inflammation and high levels of different cytokines, such as IL6, which is also associated with vitamin D3 deficiency." (PMID 39451873, 2024). "In individuals suffering from degenerative arthritis, the functionality of the IL-6 gene is associated with DNMT3A expression, and those with increased DNMT3A expression exhibit significantly lower levels of IL-6 secretion." (PMID 37626784, 2023). "An association between HIF2α and IL-6 has been reported in cancers and osteoarthritis, and studies have shown that IL-6 is the direct target gene of HIF2α in mouse articular chondrocytes." (PMID 33428604, 2021). "In patients with osteoarthritis, IL-6 gene activity is associated with the expression of DNMT3A and significantly lower levels of IL-6 secretion are found in those with DNMT3A overexpression." (PMID 33861346, 2021). "In horses, IL-6 has been implicated in equine diseases including equine metabolic syndrome and osteoarthritis, both of which tend to occur in older animals." (PMID 33668216, 2021). "AGT was observed to have a strong association with the risk of osteoarthritis (OR 3.12, 95%CI: 1.88–5.19), which remained significant even after additional adjustment with BMI, TG, sleep, IL-6, IL-1β, and CRP levels (OR 2.73, 95%CI:1.63–4.72)." (PMID 34073132, 2021). "Pro-inflammatory cytokines that cause the pathogenesis of degenerative joint diseases, including IL-1β, IL-6 and TNF-α, suppress the expression of these genes." (PMID 32030322, 2020). "This case-control study aims to examine the association between the Interleukin-6 (IL-6) rs12700386 polymorphism and the increased risk of developing osteoarthritis (OA) in the knee in the Chinese Han population." (PMID 33036557, 2020). "The epidemiological data suggest that circulating IL-6 is a significant factor in bone loss, as well as in the development of osteoarthritis-related phenotypes." (PMID 31301734, 2019). "In the knee, both TNF-α and IL-6 have been associated with knee cartilage loss and elevated IL-6 is a predictor of radiographic osteoarthritis, suggesting a link between low-level inflammation and osteoarthritis pathogenesis." (PMID 30021590, 2018). "Ex vivo treatment of peripheral blood mononuclear cells with resveratrol was associated with a dose-dependent increase in IL-6 levels only in patients with osteoarthritis." (PMID 23844973, 2013). "The aim of this study was to describe the associations between leptin, IL-6, and hip radiographic osteoarthritis (ROA) in older adults." (PMID 20482813, 2010). "Disregulated expression of IL-6 has been associated to a variety of inflammatory conditions and inflammation-induced bone loss diseases, such as osteoarthritis, reumatoid arthritis and osteoporosis." (PMID 23675187, 2010).
osteoarthritis (continued). "Additionally, IL-6 is associated with osteoarthritis related cartilage loss in and MIP-1β and IL-10 concentrations are increased in the synovial fluid of osteoarthritis patients." (PMID 41185633, 2025). "Indeed, TNF-α and IL-6 seem to be the mediators involved on the deleterious effect of vitamin D deficiency in osteoarthritis." (PMID 39940305, 2025). "However, in conditions like osteoarthritis, the synovial fluid also contains a diverse range of compounds implicated in inflammation and catabolism, such as IL6, IFNγ, MMPs, TNFα and IL-1β." (PMID 39126115, 2024). "High levels of IL-6 were also reported to induce bone loss in individuals with osteoarthritis." (PMID 38337739, 2024). "Finally, certain components of SASPs, such as TNF-α, IL-1, and IL-6, appear to be involved in the development of the pain typical of osteoarthritis, highlighting the need to investigate the underlying mechanisms." (PMID 39335461, 2024). "In addition, the hyperacetylation of H3K9/K14 and H4K12 in the IL-6 promoter region causes the elevated expression of IL-6 in synovial fibroblasts from osteoarthritis patients." (PMID 38473997, 2024). "Pro-inflammatory cytokines such as IL-1β, TNF-α, and IL-6, which are key compounds in the pathogenesis of osteoarthritis, may lead to the loss of articular cartilage homeostasis through metabolic changes and significantly accelerate joint injury." (PMID 37548663, 2024). "Numerous investigations have linked heightened IL-6 levels in circulation to the prediction of osteoarthritis and cartilage deterioration, steering the potentiation of inflammatory repercussions in affected joints and promoting the creation of enzymes that break down chondrocyte ECM." (PMID 38107476, 2023). "Other authors suggested that high preoperative levels of IL-6 might be associated with pain severity or ongoing osteoarthritis while persisting high levels of IL-6 after TKA might be a predictor of insufficient pain relief." (PMID 38098024, 2023). "The association of polymorphism with genetic disease gave us an idea about susceptibility and can also be used for early diagnosis as the study of the osteoarthritis in Pakistani population revealed that polymorphisms in IL-6, TGF-beta-1 and CALM1 genes were associated with the disease." (PMID 36451234, 2022). "The proinflammatory cytokine IL-6, characterized by elevated serum levels in osteoarthritis patients, causes deterioration of the meiotic spindle when applied to mature mouse oocytes; however, the effects were not as specific as those observed by us, and the experimental setting was quite different." (PMID 34795891, 2021). "An association between HIF2α and IL-6 has also been discovered in cancers and osteoarthritis." (PMID 33428604, 2021). "The present study affirms that susceptibility haplotype GGGGCT within the IL-6 gene influences higher plasma IL-6 levels but also confers substantial osteoarthritis risk for the knee (OR 2.10, 95%CI:1.08–3.79) after adjusting for the effects of BMI, TG, and sleep." (PMID 34073132, 2021). "Proinflammatory cytokine IL-6 is associated with joint inflammation in osteoarthritis." (PMID 34124592, 2021). "IL-6 gene polymorphisms may change gene function and expression and regulate susceptibility to osteoarthritis." (PMID 33036557, 2020). "However, IL-6 -572G>C was associated with protection in osteoarthritis and erythematosus systemic lupus." (PMID 30186038, 2018). "Additionally, a number of proinflammatory cytokines have been implicated in the pathogenesis of osteoarthritis, including IL-6, IL-17, and TNFα." (PMID 20604941, 2010). "The clustering pattern in tissue from patient 7, where the healthy and diseased gingival tissue also clustered together, could be partly explained by the patient's history of osteoarthritis, which is a disease associated with elevated levels of circulating proinflammatory cytokines IL-6 and TNFα." (PMID 23029519, 2012).